PTPRC (protein tyrosine phosphatase receptor type C)
Description:
Protein tyrosine-protein phosphatase required for T-cell activation through the antigen receptor. Acts as a positive regulator of T-cell coactivation upon binding to DPP4. The first PTPase domain has enzymatic activity, while the second one seems to affect the substrate specificity of the first one. Upon T-cell activation, recruits and dephosphorylates SKAP1 and FYN. Dephosphorylates LYN, and thereby modulates LYN activity (By similarity). Interacts with CLEC10A at antigen presenting cell-T cell contact; CLEC10A on immature dendritic cells recognizes Tn antigen-carrying PTPRC/CD45 receptor on effector T cells and modulates T cell activation threshold to limit autoreactivity. (Microbial infection) Acts as a receptor for human cytomegalovirus protein UL11 and mediates binding of UL11 to T-cells, leading to reduced induction of tyrosine phosphorylation of multiple signaling proteins upon T-cell receptor stimulation and impaired T-cell proliferation.
Synonyms: L-CA; CD45; LCA; T200; GP180; LY5; B220; CD45R; IMD105
Tractability: Small molecule: a high-quality ligand is known; it has a binding pocket of medium quality; it belongs to a druggable protein family. Antibody: a drug acting on it is in phase 2 or 3 trials; UniProt places it where antibodies can reach, with high confidence; its Gene Ontology location is reachable by antibodies, with high confidence; UniProt predicts a signal peptide or a membrane-spanning region. PROTAC: ubiquitination databases record sites on it; its protein half-life has been measured; a small molecule that binds it is known.
Target class: Tyrosine protein phosphatase; Enzyme; Phosphatase; Protein Phosphatase
Gene: Protein-coding gene on chromosome 1 (198,629,900 to 198,759,346, forward strand). Ensembl gene ENSG00000081237.
Subcellular location: Cell membrane; Membrane raft; Synapse
Subcellular location (Human Protein Atlas): Nucleoplasm; Vesicles
Pathways (Reactome):
Immune System: Neutrophil degranulation; Phosphorylation of CD3 and TCR zeta chains
Developmental Biology: Other semaphorin interactions
Gene Ontology:
Molecular function: ankyrin binding; protein binding; protein kinase binding; protein tyrosine kinase inhibitor activity; protein tyrosine phosphatase activity; spectrin binding; transmembrane receptor protein tyrosine phosphatase activity; signaling receptor binding; heparan sulfate proteoglycan binding; heparin binding
Biological process: bone marrow development; cell cycle phase transition; hematopoietic progenitor cell differentiation; negative regulation of cell adhesion involved in substrate-bound cell migration; negative regulation of interleukin-4-mediated signaling pathway; negative regulation of protein kinase activity; negative regulation of receptor signaling pathway via JAK-STAT; negative regulation of transcription by RNA polymerase II; positive regulation of B cell proliferation; positive regulation of hematopoietic stem cell migration; positive regulation of immunoglobulin production; positive regulation of stem cell proliferation; regulation of interleukin-8 production; regulation of phagocytosis; stem cell development; T cell receptor signaling pathway; B cell differentiation; B cell proliferation; B cell receptor signaling pathway; cell surface receptor signaling pathway; defense response to virus; dephosphorylation; DN2 thymocyte differentiation; natural killer cell differentiation; negative regulation of cytokine-mediated signaling pathway; and 25 more
Cellular component: bleb; cell surface; external side of plasma membrane; extracellular exosome; membrane; plasma membrane; synapse; cytoplasmic side of plasma membrane; focal adhesion; membrane microdomain; membrane raft; secretory granule membrane; cell periphery; side of membrane
Genetic constraint (gnomAD): Loss-of-function variants: 38 observed, 145.27 expected, observed/expected ratio (o/e) 0.26, 90% interval 0.2 to 0.34. The upper end of that interval is the gene's LOEUF score, 0.34, which puts it in group 1 of 6, group 1 being the genes least tolerant of losing a copy. Missense variants: 1,351 observed, 1,563.6 expected, observed/expected ratio (o/e) 0.86, 90% interval 0.82 to 0.9. Synonymous variants: 510 observed, 543.03 expected, observed/expected ratio (o/e) 0.94, 90% interval 0.87 to 1.01.
Gene-disease validity (ClinGen):
ClinGen rates the evidence that PTPRC causes each of these diseases.
immunodeficiency 104 (autosomal recessive): Definitive. A severe combined immunodeficiency characterized by being T cell-negative, B cell-positive and natural killer cell-positive and that has material basis in homozygous or compound heterozygous mutation in the IL7R gene on chromosome 5p13 or the CD45 gene on chromosome 1q31.
Homologues: Orthologues: chimpanzee PTPRC (98% identical), macaque PTPRC (89% identical), rabbit PTPRC (71% identical), guinea pig PTPRC (69% identical), mouse Ptprc (67% identical), dog PTPRC (65% identical), rat Ptprc (65% identical), pig PTPRC (56% identical), tropical clawed frog ptprc (43% identical). Paralogues in human: PTPRD (24% identical), PTPRF (24% identical), PTPRS (24% identical), PTPRM (21% identical), PTPRK (21% identical), PTPRT (21% identical), PTPRU (21% identical), PTPRZ1 (20% identical), PTPRG (20% identical), PTPRE (19% identical), PTPRA (19% identical), PTPRB (17% identical), and 23 more.
Diseases named in the same sentence as PTPRC in open-access papers:
PTPRC is named in the same sentence as 671 diseases in open-access papers, as found by Europe PMC text mining. Sharing a sentence is not in itself a finding about the gene and the disease. The quoted sentences say what the papers report.
melanoma (197 papers, 2010 to 2026). A malignant, usually aggressive tumor composed of atypical, neoplastic melanocytes. "Univariate and multivariate Cox regression analyses indicated that, compared to other clinical characteristics such as age, gender, and stage, the RiskScore based on PTPRC expression could be an independent risk factor for OS in melanoma patients." (PMID 37996489, 2023). "Targeting PTPRC may be a treatment approach for melanoma based on the hallmark immune infiltration landscape observed in our study." (PMID 37996489, 2023). "The identification of PTPRC as a core target suggests its potential role in the development and progression of melanoma." (PMID 38571962, 2024). "According to immunohistochemical data from HPA, the protein expression of PTPRC is higher in melanoma tissues than that in normal." (PMID 37996489, 2023). "Overall, we identified the value of PTPRC as an indicator of TME status remodeling in melanoma and also as a potential predictor of response to immunotherapy." (PMID 37996489, 2023). "It is important to note that while these results suggest a clear clinical link between PTPRC expression and melanoma, it has the limitation that only data from various databases the validation of mRNA levels and some simple in vitro experiments." (PMID 37996489, 2023). "In conclusion, PTPRC served as a potential predictor of survival and response to immunotherapy in melanoma patients." (PMID 37996489, 2023). "And the mRNA expression of PTPRC was upregulated in melanoma compared to adjacent tumor tissue as verified by Real-time quantitative PCR (qPCR)." (PMID 37996489, 2023). "Further bioinformatics investigations have indicated the pivotal function of PTPRC in melanoma." (PMID 38571962, 2024). "PTPRC expression was positively correlated with the levels of immune checkpoint molecules, and PTPRC knockdown significantly enhanced the migration, invasion, and proliferation of melanoma cells." (PMID 37996489, 2023). "Next, to determine whether PTPRC affects migration, invasion and proliferation of melanoma cells, siRNA targeted PTPRC was applied to knockdown PTPRC expression in A375 and MEL-28 cell lines (original blots are presented in Supplementary FigS6a, b)." (PMID 37996489, 2023). "In conclusion, it makes sense that PTPRC has been proposed as a biomarker for melanoma." (PMID 37996489, 2023). "To demonstrate the possible protective role of PTPRC in melanoma development, we showed that low expression of PTPRC enhanced the migration, invasion, and proliferation of tumor cells by knocking down the expression level of PTPRC in the melanoma cell lines A375 and MEL-28." (PMID 37996489, 2023). "Of the 466 melanoma patients in TCGA, 46 (10%) carried somatic mutations in PTPRC, and patients with PTPRC mutations had a significantly higher TMB than wild-type samples (P < 0.001), and the high-PTPRC group had a higher TMB (P = 0.029)." (PMID 37996489, 2023). "Finally, we confirmed by immunohistochemistry results in HPA and qPCR that PTPRC expression is higher in melanoma than in normal skin." (PMID 37996489, 2023). "Finally, immunohistochemical results from HPA and Real-time quantitative PCR of clinical tissues confirmed that PTPRC expression was higher in melanoma than in normal skin." (PMID 37996489, 2023). "Furthermore, another miRNA in melanoma-derived exosomes, miR-3187-3p, was also found to directly target PTPRC, a gene that encodes CD45, a key mediator of T cell receptor signaling." (PMID 32722019, 2020). "However, AUC of the receiver operating characteristic curve (ROC curve) for the PTPRC signature did not demonstrate better efficiency in predicting melanoma patient survival risk than TNM classification." (PMID 37996489, 2023). "In this study, we determined that an immune-related gene, protein tyrosine phosphatase receptor type C (PTPRC), was positively correlated with the positive prognosis of melanoma patients." (PMID 37996489, 2023).
melanoma (continued). "A recent study reported that miR-498 and miR-3187-3p in melanoma-derived exosomes inhibited the cytotoxic effect of CD8+ T cells by targeting IFN-α, protein tyrosine phosphatases receptor type C (PTPRC)." (PMID 36499102, 2022). "A previous study demonstrated that miR-498 and miR-3187-3p in melanoma-derived exosomes reduces the functions of CD8+ T cells by targeting IFN-α and protein tyrosine phosphatase receptor type C (PTPRC), the coding gene for CD45, respectively." (PMID 34827646, 2021). "Moreover, the mRNA expressions of two critical XBP1 target genes ERDJ4 and EDEM1 were also significantly correlated with PTPRC, CD8A and IFNG, respectively, indicating the potential facilitative role of IRE1α-dependent UPR branch in anti-tumor immunity in melanoma." (PMID 38291473, 2024). "Next, consideration of PTPRC expression based on TNM classification effectively improved the reliability of predicting the prognosis of melanoma patients, and thus the model may be able to provide a prediction of the prognosis of melanoma patients in the clinic." (PMID 37996489, 2023). "However, the function and mechanism of PTPRC in melanoma have not been elucidated." (PMID 37996489, 2023).
leukemia (177 papers, 2006 to 2026). A malignant (clonal) hematologic disorder, involving hematopoietic stem cells and characterized by the presence of primitive or atypical myeloid or lymphoid cells in the bone marrow and the blood. "This difference is mainly found in proteins functionally related to each pathology, for example: sCD44, HIF1A, ZMYM3 or PTPRC for CSF + LM in lymphoma and S100A9, TRAF3, KLK3, KLK2, PTPRC, among others, in the case of CSF + LM in leukemia." (PMID 35053611, 2022). "PTPRC is a key point of T/B cell antigen receptor activation in leukemia and lymphoma." (PMID 34862763, 2022). "SELL, PTPRC, IL7R, CCR7, and KLRB1 were able to distinguish leukemia cells from normal cells well, with AUC values higher than 0.970." (PMID 38165493, 2024). "PTPRC is highly expressed, and an influence of this PTP on signal transduction in leukemia was previously reported." (PMID 29507701, 2018). "Similarly, ZAP70, PTPRC, FYN and WASP2 were found to be dysregulated in different cancers including breast, leukemia, colorectal cancer, etc.." (PMID 34834481, 2021). "Notably, we found that the absence of HSP90α causes downregulation of PTPRC (or CD45) expression and restricts in vivo growth of BCR-ABL1+ leukemia cells." (PMID 38057328, 2023). "Finally, within CSF + LM group, differential protein profiles were observed between leukemia and lymphoma (such as FCGR1, CR2, ABL1, PTPRC, SELP, ITGB1, COL9A3 or ITGAX), which could subtype the CSF + LM depending on the primary tumor." (PMID 35053611, 2022).
lymphoma (165 papers, 2006 to 2026). A malignant (clonal) proliferation of B- lymphocytes or T- lymphocytes which involves the lymph nodes, bone marrow and/or extranodal sites. "Cluster 1 (top right) included genes such as CD79A, PTPRC, EZH2, MMP9, IKBKB, or CASP8, which were upregulated in GCB lymphomas (top right colored in orange)." (PMID 41472741, 2025). "All cell lines were absent for CD45 (PTPRC), a marker of hematopoietic cell lineage, suggesting none of the cell lines were derived from lymphoma." (PMID 32576280, 2020). "Other genes, such as IKBKB, PTPRC, CASP8, or CD79B, with small p-values did not have a great magnitude of changes between the lymphoma subtypes." (PMID 41472741, 2025).
breast cancer (149 papers, 2003 to 2026). A primary or metastatic malignant neoplasm involving the breast. "Those phenotypes implied PTPRC probably regulated drug sensitivity through CD8+ T cell infiltration in breast cancer." (PMID 37388747, 2023). "The genes used in the Landscape+ Breast Cancer assay were ranked according to the relationship between the expression level of the specific gene and the expression level of PTPRC." (PMID 37365600, 2023). "ICD-based subtype clustering of pan-cancer was helpful to evaluate chemotherapy sensitivity and immune cell infiltration, and PTPRC was a potential target to against drug resistance of breast cancer." (PMID 37388747, 2023). "This interaction initiated by PTPRC in breast cancer cells serves as another potential mechanism for immune escape during lymph node metastasis." (PMID 34611125, 2021). "Using PTPRC (CD45) gene expression as a proxy for total tumor leukocyte content, we identified a positive correlation between CSF-2 (GM-CSF) and CD45 in both lung and breast cancer patients." (PMID 32759497, 2020). "The plotted deconvolution results obtained from Cell2location showed high agreement with the CTA on the same breast cancer sections, which was further supported by the spatial expression of cell type markers (i.e., PTPRC for immune, FAP for stroma, and EPCAM for tumor) in the same tumor regions." (PMID 40925915, 2025). "In addition to bioinformatic analysis, MIF assays also showed that the expression strength of PTPRC in breast cancer cells was positively related to CD8 expression strength in breast cancer tissue section (R=0.85, p=1.75e-5)." (PMID 37388747, 2023). "PTPRC enhances immune responses mediated by CD8+ T cells and increases drug sensitivity in breast cancer treatment." (PMID 39845086, 2024). "The chosen primer/probe sets were combined into a single model assay (71 breast cancer genes and the WBC marker PTPRC) (the Landscape+ Breast Cancer assay) for evaluation of the gene expression method." (PMID 37365600, 2023). "PLA2G2A was also positively correlated with the CD45 antigen PTPRC, B-cell marker CD79A, and CD8 T cell marker CD8A in breast cancer patients." (PMID 36357424, 2022).
colitis (79 papers, 2008 to 2025). Inflammation of the colon. "Furthermore, in the trinitrobenzene sulfonic acid-induced colitis model, increased immunoreactivity of PTPRC was detected." (PMID 37638002, 2023). "However, in PTPRC knockout mice, colitis follows dietary changes." (PMID 37638002, 2023).
myeloma (71 papers, 2006 to 2026). "For instance, in the multiple myeloma cell line U266, CD45 (termed PTP receptor type C; PTPRC) shapes the IL‐6 control of cellular adhesion and proliferation." (PMID 34618359, 2022).
lung carcinoma (61 papers, 2013 to 2026). "There is a lot of data showing that LAPTM5 and PTPRC are not only co-expressed in AD/PD, but also in systemic lupus erythematosus, lung cancer, and other diseases." (PMID 35912089, 2022). "MPE-Mφ showed relatively higher expression levels of M1 (IL-1β, IL-6, and CXCL10), M2 (CCL18 and IL-10), and pan-macrophage markers (CSF1 and PTPRC) compared to MDMs from lung cancer patients or HCs." (PMID 33175182, 2021). "Cell cluster-specific genes coalesced the 25 clusters into four major groups: CNV−MOG+ normal glial cells, KRT5+ lung cancer (LC) metastasis cells, CD45 (PTPRC)+ immune cells and CNV+ malignant tumor cells." (PMID 34692159, 2020). "However, the mechanism of PTPRC in lung cancer has not been elucidated." (PMID 33520448, 2021).
COVID-19 (57 papers, 2020 to 2025). A disease caused by infection with severe acute respiratory syndrome coronavirus 2. "Through the analysis of transcriptome data, PTPRC was shown to be an important inflammatory and immunomodulatory signature in COVID-19, and that it has high binding efficiency with related drugs in clinical transformation research." (PMID 38455049, 2024). "PTPRC is revealed as a new biomarker for SARS-COV-2 pathogenesis through the analysis of various transcriptomic datasets from COVID-19 patients." (PMID 38104081, 2023). "We observed dramatically decreased protein levels of protein tyrosine phosphatase receptor type C, leptin, and tartrate-resistant acid phosphatase type 5, which are involved in lymphopenia, and platelet basic protein in COVID-19 patients." (PMID 33203833, 2020). "Severely affected COVID-19 patients have lower levels of the PTPRC gene, indicating that activation of nave B cells may be hampered in these people." (PMID 37521843, 2022). "Specifically, in the COVID-19 patient’s B cells, we detected a substantial increase in the expression of CD52, CD74, CD22 and CD79B and a decrease in CXCR4, CD69, INFGR1, PTPRC and LAMP1 transcripts with respect to control-derived B cells." (PMID 34944610, 2021).
ovarian carcinoma (55 papers, 2005 to 2026). A malignant neoplasm originating from the surface ovarian epithelium. "In the present study, we evaluated a potential association of C77G in PTPRC with ovarian cancer in Norwegian patients." (PMID 28759630, 2017). "On the 10 × Genomics Visium human ovarian cancer dataset (downloaded from the 10 × website), the PTPRC (CD45) gene expression showed poor correlation (0.193) with the protein expression from immunofluorescent (IF) staining." (PMID 38217035, 2024). "Protein-protein network interactions exhibited PTPRC, ITGAM, and CCR5 were most related to the modulation and function of the differentially expressed CBXs family members in ovarian cancer." (PMID 35155439, 2022). "Therefore it was tempting to hypothesise that C77G could be associated with ovarian cancer risk in general, although the harbouring gene PTPRC is not expressed in tumour cells, but restricted to lymphocytes." (PMID 28759630, 2017). "Among the genes we identified in this study, IL7R, IRF8, PTPRC, and NSG1 have not been thoroughly explored or recognized for their relevance in ovarian cancer recurrence in previous studies." (PMID 41596598, 2026).